CRP (C-reactive protein)
Diseases named in the same sentence as CRP in open-access papers (continued):
Sharing a sentence is not in itself a finding about the gene and the disease.
Hypercholesterolemia (116 papers, 2009 to 2025). An increased concentration of cholesterol in the blood. "Genetically determined CRP was robustly associated with increased risk of vascular dementia, bipolar affective disorders, pure hypercholesterolemia, and neurological diseases." (PMID 34386016, 2021). "In the present paper, whole blood leukocyte distribution and plasma inflammatory proteins were measured for association with cholesterol concentration and CRP in children with familial hypercholesterolemia (FH) and healthy children." (PMID 28070551, 2017). "Increased CRP levels exhibit synergy with concurrent hypercholesterolemia to increase CVD risk in both men and women." (PMID 24578648, 2014). "In addition to induction of oxidative stress, hypercholesterolemia in the present study was associated with increased serum proinflammatory cytokines and CRP." (PMID 30363969, 2018). "In adults with hypercholesterolemia, a purified anthocyanin mixture led to significant reductions in serum CRP, sVCAM-1, and plasma IL-1β compared to a placebo." (PMID 41156509, 2025). "We found significant differences in serum TC (p<0.001), TG (p=0.006), LDL-C (p<0.001), and CRP level (p=0.007) between the normocholesterolemia and hypercholesterolemia groups." (PMID 39469407, 2024). "People with subclinical hypothyroidism have a higher increased risk compared to euthyroid patients of developing hypercholesterolemia, increased levels of LDL-c and CRP, and elevated diastolic blood pressure." (PMID 38667716, 2024). "The difference was not statisticallysignificant, despite the fact that a larger proportion of hypercholesterolemia patients had increased C-reactive protein levels." (PMID 40092874, 2024). "us-CRP suggested an incipient inflammatory state, and their lipid profiles denoted moderate hypercholesterolemia and hypertriglyceridemia." (PMID 36769628, 2023). "It has been shown that statin therapy lowers CRP and/or circulating pro-inflammatory cytokines’ levels in patients with hypercholesterolemia and familial combined hyperlipidemia." (PMID 34768528, 2021). "Genetically determined CRP levels also positively affected pure hypercholesterolemia though it was insignificant in the UK Biobank cohort." (PMID 34386016, 2021). "For the phenotypes that passed the FDR correction in UK Biobank, the scatter plot showed that a strong outlier (rs4420638) altered the effects of CRP on AD and hypercholesterolemia and others." (PMID 34386016, 2021). "The scatter plot showed that the same strong outlier (rs4420638) altered the effects of CRP on these diseases except for pure hypercholesterolemia and neurological diseases." (PMID 34386016, 2021). "Further, the inflammatory markers (CRP, IL-6, and α-TNF) were significantly elevated in the serum of the PG group when compared with the NG group (p < 0.05) confirming the association of hypercholesterolemia with inflammation." (PMID 33202660, 2020). "As anti-inflammatory agents, statins cause downregulation of inflammatory cytokines and reduce the concentrations of C-reactive protein (CRP) in hypercholesterolemia, as observed in the mice from the HLS group in this study." (PMID 32881885, 2020). "DM and hypercholesterolemia influence the association between carotid IMT and C-reactive protein, a biomarker of inflammation." (PMID 30941360, 2019). "It is intriguing that the relationship between cholesterol level and CRP level remains very weak even with statin therapy, even with the fact that hypercholesterolemia induces systemic inflammation." (PMID 31885691, 2019). "The elevated levels of CRP in animals with experimentally induced hypercholesterolemia, demonstrated in the current study, are consistent with the available published data." (PMID 29713239, 2018). "There is data to confirm extrahepatic origin of CRP in rabbits with experimentally induced hypercholesterolemia, as its synthesis in adipocytes was shown to be inhibited by administering atorvastatin." (PMID 29713239, 2018).
Hypercholesterolemia (continued). "We also analyzed inflammation (CRP and fibrinogen), and metabolic (glycated hemoglobin, hypercholesterolemia and microalbuminuria) parameters but we found that the CFVR and CS were the only independent predictors of adverse events." (PMID 26340922, 2015). "Univariate analysis showed that the risk factors of hs-CRP, LDL-C, fasting blood sugar, hypercholesterolemia, MS, and hyperuricemia played a significant role in CAD (P<0.05)." (PMID 25184207, 2014). "Further adjustment for eGFR, hypercholesterolemia, HbA1c, lipid parameters, CRP, or coronary revascularization following baseline angiography (PCI or CABG) only minimally affected the estimate (data not shown)." (PMID 23346455, 2012). "Moreover, MR studies on CRP and hypercholesterolemia have yielded varied results across different populations." (PMID 39859220, 2025). "The following parameters were tested: sex, age, LDL, hypercholesterolemia, smoking, BMI, and CRP." (PMID 39857612, 2024). "Based on these results, we postulated that subclinical inflammation, as measured by circulating CRP and omega‐6 and omega‐3 FAs, and educational attainment might mediate the links of higher BMI and/or hypercholesterolemia with altered LTL." (PMID 37415075, 2023). "The data suggest that hypercholesterolemia- induced increase in CRP couldalso be involved in the development of hypercholesterolemic atherosclerosisthrough generation of numerous atherogenic biomolecules." (PMID 39077184, 2022). "Lowering of AGE and C-reactive protein, raising of sRAGE, anduse of antioxidants may be considered as an adjunct therapy besides lipidlowering agents for the treatment of hypercholesterolemia." (PMID 39077184, 2022). "Furthermore, a moderate negative correlation between some regions of interest temperature change caused by dry CO2 baths and health-related characteristics, such as CRP, fasting glucose and hypercholesterolemia state, was identified." (PMID 33557430, 2021). "Furthermore, the rs2708965, rs2708962, rs6717710, rs2708961, and rs2708960 are related to high levels of C-reactive protein(CRP) in individuals with hypercholesterolemia." (PMID 34248996, 2021). "Furthermore, given the close link between inflammation and hypercholesterolemia, we tested the interaction between CRP and LDL-cholesterol in the multivariate model (P interaction = 0.005)." (PMID 33947397, 2021). "Additionally, the extract significantly inhibited hypercholesterolemia and hs-CRP in overweight/Class-1 obese adult subjects from the US population." (PMID 25756303, 2015). "Therefore in this study we examined plasma levels of insulin, C-reactive protein (CRP) and total NO metabolites (NOx), as well as fatty streak formation in the rabbit model of hypercholesterolemia." (PMID 23497719, 2012). "In addition, hypercholesterolemia may induce CRP secretions in adipocytes, by reducing the expression of peroxisome proliferator-activated receptor (PPAR-γ)." (PMID 25215291, 2014). "In conclusion, hypercholesterolemia induces atherosclerosisthrough increases in atherogenic biomolecules, AGE-RAGE axis and CRP." (PMID 39077184, 2022). "Nonetheless, the relationship between CRP and efflux shows some promise for garlic as a CAD therapy, with more research warranted for those with hypercholesterolemia." (PMID 34239993, 2021). "We examined alteration of plasma levels of insulin, C-reactive protein (CRP) and total NO metabolites (NOx), as well as fatty streak formation in the rabbit model of hypercholesterolemia." (PMID 23497719, 2012). "None of the participants without hypercholesterolemia had C-reactive protein levels below 7 mg/L, and 31.82% had levels of 7 mg/L orhigher." (PMID 40092874, 2024). "Hypercholesterolemia could also produceatherosclerosis through increases in AGE, AGE/sRAGE and CRP, and decreases in thelevels of sRAGE." (PMID 39077184, 2022).
Hypercholesterolemia (continued). "It is surprising that there are limited publications on the effects ofhypercholesterolemia on C-reactive protein and AGE-RAGE axis.Hypercholesterolemia increases the production of AGE, CRP, and ROS, and decreasesthe production of sRAGE all of which are implicated in the formation ofatherosclerosis." (PMID 39077184, 2022). "For the CO2 group, statistical analysis revealed a negative correlation between some regions of interest and CRP, fasting glucose and hypercholesterolemia state." (PMID 33557430, 2021). "In contrast, a recent study on the mechanism of CRP reduction by statins, a drug used for the treatment of hypercholesterolemia, indicated that its production was not reduced but the fractional catabolic rate was enhanced." (PMID 27456968, 2016). "The aim of the study was to assess the effect of 5α,6α-epoxycholesterol on experimentally induced hypercholesterolemia in rabbits, and the levels of homocysteine (HCY), asymmetric dimethylarginine (ADMA), paraoxonase-1 (PON-1), and inflammatory parameters (IL-6, TNF-α, CRP)." (PMID 29713239, 2018). "In our present study, CRP, which is a marker of pleiotropic effects of statins, were significantly lower in those with hypercholesterolemia than those without (1.52 ± 3.72 vs. 2.23 ± 4.40 mg/dL, P = 0.024) among 746 patients whose serum CRP levels were measured on admission." (PMID 28352408, 2012). "Daily phytosterol intake of 3.0 g of phytosterol-supplemented margarine during 18 weeks showed no changes in inflammatory biomarkers (CRP, SAA, IL-6, IL-8, TNF-α, and soluble intercellular adhesion molecule-1) compared to placebo in patients with hypercholesterolemia." (PMID 31068933, 2019). "Studies also reported beneficial effects on C-reactive protein (CRP) lowering (as reviewed by Liao), and specifically, the JUPITER study pointed out that subjects with increased CRP without hypercholesterolemia could benefit from statin therapy, regardless of LDL levels." (PMID 29670468, 2018).
osteomyelitis (116 papers, 2008 to 2026). An acute or chronic inflammation of the bone and its structures due to infection with pyogenic bacteria. "In general, acute osteomyelitis is associated with elevated leukocytes, neutrophils, and C-reactive protein (CRP)." (PMID 41142568, 2025). "Toe ulceration, elevated C‐reactive protein (CRP), and the presence of osteomyelitis were associated with surgical management." (PMID 38797920, 2024). "This study has found that elevated CRP levels, ulcer location on the toe, and osteomyelitis are strongly associated with surgical interventions during hospital admission." (PMID 38797920, 2024). "Three weeks later, she presented with recurrent shoulder pain associated with fever, swelling, elevated CRP, and osteomyelitis changes of the humeral head on a plain radiograph." (PMID 37671211, 2023). "The aim of this study was to determine the diagnostic accuracy of ESR and CRP in detection of diabetic foot cases with osteomyelitis." (PMID 33134967, 2020). "SAB with deep-seated foci such as osteomyelitis has been associated to higher CRP levels compared to intravenous catheter-related infections before, while the inverse dynamic of fever is an interesting additional finding for which we found no previous evidence." (PMID 33800644, 2021). "Enhanced lumbar magnetic resonance imaging (MRI) demonstrated spondylodiscitis and osteomyelitis at L1-L2 with bilateral psoas extension, and his C-reactive protein (CRP) level was elevated at 38.68 mg/L." (PMID 41293351, 2025). "Most clinical decisions based on ESR only (5/6, 83%) or CRP only (3/4, 75%) were in bone and joint infections (osteomyelitis or septic arthritis)." (PMID 40109915, 2025). "While ESR is better at ruling out osteomyelitis initially, CRP helps distinguish osteomyelitis from soft tissue infection in patients with elevated ESR." (PMID 39208074, 2024). "Patients with elevated CRP levels, a forefoot diabetic ulcer and established osteomyelitis were more likely to undergo surgical management." (PMID 38797920, 2024). "Factors associated with surgical management in univariate analysis were HbA1c, CRP level, presence of osteomyelitis in diabetic foot ulcers, and length of stay." (PMID 38797920, 2024). "CRP levels of 1-4.9 mg/dL were mainly found in patients with osteomyelitis (50%, N=two) and both osteomyelitis and VOC, or hemolytic crisis (25%, N=one)." (PMID 39238724, 2024). "Multivariate analysis calculated an odds ratio (OR) of 1.01 for CRP (p < 0.001), OR 2.19 (p < 0.019) favouring surgical management for forefoot ulcers, and OR 2.2 (p < 0.019) if osteomyelitis was present." (PMID 38797920, 2024). "Another study led by Fujii M. retrospectively studied 30 patients with CLTI and forefoot osteomyelitis and recommends, as the first therapeutic intention, debridement and infection clearance if a CRP level greater than 40 mg/L is identified." (PMID 38672153, 2024). "Increased association with surgical management (OR >1) were found in four data points: HbA1c, CRP level, presence of osteomyelitis, and length of stay." (PMID 38797920, 2024). "While ESR serves as a more sensitive option, CRP has been reported to have the ability to differentiate between osteomyelitis and soft tissue infection, with a cutoff value of >7.9 mg/dL66." (PMID 39554800, 2023). "The elevated neutrophils and C-reactive protein levels indicated bacterial infection, and the local color ultrasound results made us further consider the possibility of osteomyelitis." (PMID 37390234, 2023). "Children with discitis rarely presented with fever and had lower CRP values on admission compared to children with osteomyelitis and bacterial arthritis." (PMID 36201153, 2023). "Positive osteomyelitis bone biopsy results typically include elevated C-reactive protein (CRP), erythrocyte sedimentation rate (ESR), with presence of causative organism (typically S. aureus)." (PMID 36015188, 2022).
osteomyelitis (continued). "As with other forms of osteomyelitis, patients with vertebral osteomyelitis also present with elevated inflammatory marks of C-reactive protein (CRP) and erythrocyte sedimentation rate (ESR)." (PMID 36015188, 2022). "Based on one-way ANCOVA, there was no dependency on the time to normalization of WBC count, ESR and CRP levels on independent variables such as sex, age, region of osteomyelitis, bacterial culture, and baseline WBC, ESR and CRP levels." (PMID 36564738, 2022). "While IL-6 is recognized to be produced throughout the course of osteomyelitis, and has been found to be similarly useful in diagnosis of chronic osteomyelitis as C-reactive protein (CRP) and erythrocyte sedimentation rate (ESR)." (PMID 36726643, 2022). "Normal CRP (<0.5 mg/dL) were observed in 46/205 (22.12%) children; 4/21 (22.12%) with spondylodiscitis, 3/12 (25.00%) with neonatal osteomyelitis and 39/172 (22.29%) with osteomyelitis of another type." (PMID 34438507, 2021). "In clinical tests for osteomyelitis diagnosis, conventional laboratory parameters are C-reactive protein (CRP), erythrocyte sedimentation rate (ESR), and white blood cells (WBCs)." (PMID 32793507, 2020). "It has also been shown that in patients with high ESR levels, CRP aids to distinguish osteomyelitis from soft tissue infection." (PMID 32566310, 2020). "The findings of this study showed that on average, the values of all inflammatory markers, including ESR and CRP, show an increase in patients with diabetic foot infections and higher values were found in patients with osteomyelitis." (PMID 33134967, 2020). "Based on the findings of ROC curve analysis, ESR and CRP had fair and poor accuracy, respectively, in detecting the diabetic foot cases with osteomyelitis." (PMID 33134967, 2020). "The present study aimed to evaluate the diagnostic value of erythrocyte sedimentation rate (ESR) and C reactive protein (CRP) in detection of osteomyelitis in patients with diabetic foot." (PMID 33134967, 2020). "Based on the findings of ROC curve analysis the ESR and CRP had fair and poor accuracy, respectively, in detecting diabetic foot cases with osteomyelitis." (PMID 33134967, 2020). "A prospective study of 265 children with osteomyelitis and septic arthritis reported a mean CRP value of approximately 87 mg/L and a mean ESR value of approximately 51 mm/h at the time of presentation." (PMID 32781552, 2020). "The findings of this study showed that the predictive value of ESR and CRP in detecting osteomyelitis is desirable." (PMID 33134967, 2020). "The sensitivity and specificity of CRP (cut-off value >14 mg/L) in diagnosis of osteomyelitis were 0.85 and 0.83." (PMID 33134967, 2020). "The best cutoff points of PCT, ESR and CRP in predicting osteomyelitis were 0.35 ng/ml (86.1% sensitivity, 45.3% specificity), 56.5 mm/hours (95.8% sensitivity, and 50.0% specificity) and 44 mg/ml (90.3% sensitivity, 57.0% specificity), respectively." (PMID 31555767, 2019). "The workup for suspected osteomyelitis includes a thorough history and physical, lab evaluation including white blood cell count, C-reactive protein (CRP), erythrocyte sedimentation rate (ESR), blood cultures, and radiographic imaging." (PMID 31187004, 2019). "This study was a randomized, open-label, comparator-controlled trial in adults with a first episode of osteomyelitis defined by clinical symptoms, radiologic findings, and elevated C-reactive protein." (PMID 30648126, 2019). "Several studies have been conducted on the relationship of increase in ESR and CRP with predicting osteomyelitis in diabetic patients, but few studies have been done on the role of PCT in predicting osteomyelitis." (PMID 31555767, 2019). "The areas under the ROC curve of PCT, ESR and CRP in predicting osteomyelitis were 0.787, 0.869, and 0.907, respectively; showing high predictive value for each biomarker." (PMID 31555767, 2019).